HSPA5 (heat shock protein family A (Hsp70) member 5)
Diseases named in the same sentence as HSPA5 in open-access papers (continued):
Sharing a sentence is not in itself a finding about the gene and the disease.
tumor (continued). "The Basal subtype showed the highest number of specific upregulated genes (DNAJC2, DNAJC6, HSPA5, HSPA14 and CRYAA), DNAJA3 and CCT2 were upregulated in Luminal B, and DNAJB3 was only upregulated in HER2 tumours." (PMID 29954368, 2018). "All five of the proteins predicted to be upregulated in EAC compared with normal esophagus (SAMHD1, ARHGDIB, AGR2, HSPA5, EPCAM) showed higher expression in the tumor sections compared with squamous epithelium." (PMID 28336725, 2017). "We also observed a downregulation of stress response proteins (HSPA1A/HSPA1B, HSPA5, SERPINH1), suggesting that TSA might affect cellular stress response pathways, potentially impacting tumor cell survival." (PMID 40429900, 2025). "Resting tumour cDC1s included cluster 5 enriched in transcripts involved in the unfolded protein response (UPR) such as Creld2, Hspa5, and Pdia6, as well as the clusters 2, 3 and 6 that expressed transcripts such as Fos, Jun, and Dusp1 and cluster 0 that expressed H2afz, Lyz2, Sub1." (PMID 40745918, 2025). "S100A9, which we found up-regulated in pT1-HG biopsies, was identified as a protein associated with iNOS activity, and it is also involved in the regulation of signal transduction, such as SOD2, APOA1, HSP90, HSPA5, HINT1, MYDGF, and SerpinB3, and in immunomodulation in tumor microenvironments." (PMID 41441336, 2025). "MET, GPI, ANGPTL4, HSPA5, TGFA, MIF, and ARTN were significantly up-regulated in tumor samples." (PMID 36447119, 2023). "In summary, pharmacological inhibition or knock‐down of HSPA5 reverted the enhanced malignancy of NRF3‐KO cells, demonstrating that the tumor‐suppressive function of NRF3 depends on its binding partner HSPA5 and the reduction in the levels of this pro‐tumorigenic UPR protein." (PMID 37807968, 2023). "Finally, the Tumor Immune Estimation Resource (TIMER) method was adopted to explore the relation between immune infiltration and HSPA5 in BC." (PMID 36193502, 2022). "In the current study, HSPA5 has been found to be highly expressed in almost all the normal tissues and increased in most tumor tissues, indicating that all the organs will be potentially infected, higher susceptible to SARS-CoV-2 in those with tumors." (PMID 33767597, 2021). "What is unusual is that even when grown in vitro where no noxious factors are present, tumor cells continue to express high levels of HSPA5." (PMID 34943954, 2021). "But the tumor patients with its receptor expression files for HSPA5 in this outbreak have not been reported." (PMID 33767597, 2021). "(A) mRNA expression of ER-stress markers Edem1, Ero1b, Grp94, Herp, Atf4, Eif2ak3, Ddit3, and Hspa5 in liver tissue from healthy mice; and tumor tissue and surrounding non-tumoral tissue from mice with DEN-induced HCC." (PMID 33103995, 2020). "This confirmed that tumor cells secrete factors that induce mRNA-expression of EIF2AK3, DDIT3, HSPA5, spliced XBP1, and HSPA5, as well as protein expression of p-IRE1α in hepatic stellate cells co-cultured with tumor cells, indicating the presence of ER-stress." (PMID 33103995, 2020). "In view of BC-related function of these BLBC-specifically secreted proteins, several factors involved in tumor progression and metastasis showed increased secretion, including CD44, heat shock protein family A member 5 (HSPA5), and heat shock protein 90 beta family member 1 (HSP90B1)." (PMID 31146747, 2019). "The anti-tumor response to the combination of curcumin and OPCs in mice xenograft tumors and organoids derived from primary human CRC tumors correlated with the altered gene expressions of HSPA5, IHH, PDE3B, cyclin D1 and SEC61B." (PMID 30218018, 2018). "HSPA5 expression was found significantly elevated in recurrent GBM specimens following treatment with chemotherapeutics and radiation compared with normal brain tissue, suggesting a potential link between increased protein expression and both tumor recurrence and resistance to chemo-radiotherapy." (PMID 41002413, 2025).
tumor (continued). "An antibody targeting the C-terminus of HSPA5 has been shown to suppress the proliferation of GBM cells and induce apoptosis by inhibiting the PI3K/AKT/mTOR signaling pathway in vitro, and to delay tumor growth in a heterotopic tumor mouse model when combined with ionizing radiation." (PMID 41002413, 2025). "Thus, the tumor-suppressive effects of SBSPON, at least partially, were achieved through suppressing the phosphorylation of AKT by inhibiting the membrane translocation of HSPA5, thereby inhibiting HSPA5's promoting effect on tumors." (PMID 40765821, 2025). "In the future, it will be important to determine if NRF3 and HSPA5 directly bind to each other, how the interaction of NRF3 with HSPA5 regulates the amount and localization of this ER chaperone, and if additional mechanisms contribute to the tumor‐suppressive effect of NRF3 in keratinocytes." (PMID 37807968, 2023). "We also identified six proteins (CALR, HIST2H2AC, HSPA5, P4HB, and PDIA6) in the HPA database that showed increased immunostaining in PCa tumor tissue, while low or not detected in normal prostate tissue." (PMID 33049715, 2020).
infection (146 papers, 2008 to 2026). The state of being infected such as from the introduction of a foreign agent such as serum, vaccine, antigenic substance or organism. "We found that at 4 h post-infection (p.i.), NP in the nucleus were observed in 60% of scrambled shRNA-treated cells, but only detected in 20% of HSPA5-specific treated cells and 10% of HSPA8-specific shRNA-treated cells." (PMID 40559543, 2025). "This highlights the importance of further work using HSPA5 knockout cell lines or animal models to evaluate its precise role in infection and therapeutic potential." (PMID 41303479, 2025). "Taken together, our data showed that SEPT2 promotes the acetylation of HSPA5 by recruiting the acetylase ATAT1 and that acetylated HSPA5 is critical for controllable M1-like activation and the inflammatory response during infection." (PMID 37978190, 2023). "Taken together, these data showed that K327-acetylated HSPA5 is beneficial for avoiding SEPT2-deficiency-induced excessive M1-like hyperactivation and excessive inflammation upon infection." (PMID 37978190, 2023). "As expected, BiP/HSPA5 expression increased 48 h after infection in both human and monkey cell lines." (PMID 36851505, 2023). "How then does infection with Legionella activate HSPA5/BiP transcript induction to a degree similar to that induced by the ATF6-N fragment?" (PMID 34635501, 2021). "Recently virtual screening studies revealed that known HSPA5 inhibitors interferes with the infection by SARS-Cov-221." (PMID 33767597, 2021). "By comparing transcriptional dynamics in DENV versus ZIKV infected cells, we observed great differences in the specificity of these cellular factors for either virus, with a few genes including ID2 and HSPA5 playing opposite roles in the two infections." (PMID 29451494, 2018). "Infection of RAW-Control cells with H37Ra increased the levels of Hspa5, P-eIF2α, and CHOP, when compared with uninfected counterparts." (PMID 28969051, 2017). "HSPA5 was also found to co-localize with CV-A9 at the SW480 cell periphery during the early stages of infection by confocal microscopy." (PMID 27756316, 2016). "An infection model using green monkey kidney cell line has been proposed by which CV-A9 utilizes the αVβ3 integrin as its primary attachment receptor and HSPA5 as its co-receptor." (PMID 27756316, 2016). "Indeed, normalized gene expression from paw tissue revealed greater levels of cytokines and a trend for Hspa5 and Ddit3, suggesting that the paws had a relatively greater burden of infection compared to spleen." (PMID 40366144, 2025). "Interestingly, NP levels became significantly elevated at later stages of infection in HSPA5 knockdown cells, which was further supported by immunofluorescence microscopy showing intracellular accumulation of NP proteins." (PMID 41303479, 2025). "Through bioinformatic approaches, we predicted the binding mode and key binding residues between HSPA5 and the GoAstV-P2 protein, laying the theoretical foundation for further investigation into the role of HSPA5 as an interaction protein or co-receptor in GoAstV infection mechanisms." (PMID 40433662, 2025). "Interestingly, levels of viral structural proteins increased in HSPA5 KD cells after infection." (PMID 41303479, 2025). "We then examined the acetylation level of HSPA5 at 6 h and 12 h post-infection and found that HSPA5 could not be further acetylated in SEPT2-deficient PMs." (PMID 37978190, 2023). "Moreover, after 5 min post-infection, a clear co-localization (40 %) between the HSPA5 and CV-A9 was detected at close vicinity to the inner surface of plasma membrane, further suggesting that HSPA5 has a role in the CV-A9 attachment to the cell surface and in the early stage of the internalization." (PMID 27756316, 2016).
infection (continued). "This fluctuation contrasts with certain HSP70 isoforms, where several are upregulated (e.g., HSPA1L, HSPA2, HSPA5, HSPA9, HSPA12, and HSPA13), while others from the HSP70 family are downregulated post-peak infection phase (Chand, Iyer & Mitra, 2021)." (PMID 39308823, 2024). "When unfolded protein accumulates due to mild infection, SEPT2 expression is induced due to activation of the IRE1 pathway; additionally, SEPT2 can suppress ER stress by promoting the acetylation of HSPA5." (PMID 37978190, 2023). "Immunohistochemical results showed that the expression of HSPA5, Ki-67 and BCL2 decreased, and the expression of autophagy marker LC3B decreased and the expression of P62 increased after LV-miR-197-3p infection." (PMID 35342334, 2022). "In primary NHBE cells, pre-infection priming with TG enhanced expression of the ER stress genes (DDIT3, HSPA5 and HSP90B1), relative to the DMSO control, before and during RSV infection in a TG dose-dependent manner." (PMID 33546185, 2021). "In this study, HSPA5, HSPA1B, HSP90B1 and HSPA6 were up-regulated at 24 hpi to various degrees following CPIV3 -infection of MDBK cells." (PMID 31101113, 2019). "Five unique heat shock proteins (HSP75, HSP90A, HSPA2, HSPA5 and HSPA8) were identified during rNA-wt infection." (PMID 28079188, 2017). "The reduction of HSPA5 expression likely delayed or inhibited the attachment or internalization of the virus particle, consequently leading to the observed reduction in NS1 and NP expression during the early stages of infection." (PMID 41303479, 2025). "Therefore, the influence of PCV2 and PRV coinfection on ER activation, especially the role of GRP78 (HSPA5), eIF2α, and ATF4 in the infection, will be verified in the follow-up research." (PMID 35562870, 2022). "HSPA5 KD, PSMA2 KD and IGFBP5 KD remained stable throughout the course of infection." (PMID 36680137, 2022). "Moreover, infection of monocytes by HRV upregulates ORMDL3 (a sphingolipid biosynthesis regulator), leading to increased levels of IFN-β and the endoplasmic reticulum chaperone BiP (HSPA5)." (PMID 32704466, 2020). "The data suggest that while αVβ6 integrin is essential for CV-A9 in A549 cell line, it is not required in SW480 cell line in which β2M and HSPA5 alone are sufficient for CV-A9 infection." (PMID 27756316, 2016). "Indeed, Borna disease virus (BDV) interacts with surface-exposed HSPA5 through the GP1 capsid protein, and antibodies directed against the N-terminus of HSPA5 protein have also been shown to inhibit the binding and infection of the dengue virus serotype 2." (PMID 27756316, 2016). "The results showed that VSV infection could enhance the co-localization of SEPT2 and HSPA5 as expected; however, the co-localization of ER and SEPT2 was not significantly changed upon infection." (PMID 37978190, 2023).
neurodegenerative disease (16 papers, 2013 to 2024). A disorder of the central nervous system characterized by gradual and progressive loss of neural tissue and neurologic function. "The suppression of HSPA5 protein and UPS signal is one of the neuroprotective approaches in treating neurodegenerative diseases, i.e., PD and AD." (PMID 36364894, 2022). "By regulating SQSTM1 and HSPA5 ubiquitination and regulating SQSTM1 activity, UBE2D3 could potentially contribute to clearance of aggregates and thereby help in reducing the chance of development of neurodegenerative diseases." (PMID 37059365, 2023).
breast (6 papers, 2016 to 2025). "Comparisons of RNAseq findings between HCT116- and HT29-derived tumorspheres revealed that HSPA5 were mediated by the STAT3-miR-30a-5p axis, which is overexpressed in colorectal tumorspheres associating to anti-apoptosis." (PMID 33023006, 2020).
infectious disease (1 paper, 2019). A disorder directly resulting from the presence and activity of a microbial, viral, or parasitic agent in humans. "Additionally, some of these target genes, including SOD2, TNFAIP3, ARG1, SERPINB2, VLDLR, HSPA5, and LCN2, are associated with infectious diseases, suggesting that lncRNAs respond to PCV2 infection by regulating these genes." (PMID 30863688, 2019).
HSPA5 also shares sentences with these, for which no sentence is quoted: Insulin resistance (26 papers); rheumatoid arthritis (24); lung adenocarcinoma (17); atherosclerosis (16); metabolic disorders (15); mucormycosis (15); multiple myeloma (15); heart failure (13); renal cell carcinoma (13); cardiac hypertrophy (12); malignant glioma (12); pulmonary fibrosis (12); steatosis (12); brain tumor (11); dementia (9); depression (9); Hypoglycemia (9); ischemic stroke (9); type 1 diabetes (9); ischemia (8); kidney disease (8); metabolic syndrome (8); preeclampsia (8); endothelial dysfunction (7); esophageal cancer (7); Hyperinsulinemia (7); liver fibrosis (7); ovarian tumors (7); pneumonia (7); Arthritis (6).
A further 312 diseases each share a sentence with HSPA5 in 6 papers or fewer.